CRP (C-reactive protein)
Diseases named in the same sentence as CRP in open-access papers (continued):
Sharing a sentence is not in itself a finding about the gene and the disease.
diabetes (continued). "We also included fasting glucose and CRP to the models to ensure that factors in the subclinical phase of diabetes development were not responsible for the raised levels of follistatin." (PMID 34759311, 2021). "In the subgroup of diabetes, patients with elevated LDH or reduced lymphocytes had a lower survival rate compared with the controls; meanwhile, a trend toward lower survival rate was observed in patients with elevated CRP and D‐dimer." (PMID 33112011, 2021). "The binary logistic regression analysis showed that NLR was significantly associated with HFpEF, independent of effects of age, gender, BMI, hs-CRP, and diabetes (adjusted OR, 2.351; 95% CI, 1.464–3.776; p < 0.001)." (PMID 34250033, 2021). "CI: confidence interval; CRP: C-reactive protein; T2DM: type 2 diabetes mellitus." (PMID 33728195, 2021). "Although gout contributes to insulin resistance and increased levels of CRP 33, gout did not increase the risk of CAS-related diabetes." (PMID 34104095, 2021). "On multivariate logistic regression analysis adjusted for age, sex, diabetes mellitus, hypertension, body mass index, hemoglobin, RDW-CV, eGFR, uric acid, CRP, proteinuria, and contrast volume, low PNI was independently associated with an increased risk of AKI (OR 0.96, 95% CI 0.94–0.98, P = 0.001)." (PMID 33782522, 2021). "According to a recent meta-analysis, saffron is effective in improving the levels of inflammatory markers such as TNF-α, IL-6 and CRP when administered at specific doses (≤30 mg/day) in young adults (<50 years old) lacking a diabetes diagnosis." (PMID 34959826, 2021). "The other study evaluated an 8-week dose of 6 mg melatonin versus placebo in type 2 diabetes mellitus patients with severe periodontitis and found a reduction in PD, CAL, and serum levels of IL-6 and CRP in the test group along with an increase in serum melatonin levels." (PMID 34066498, 2021). "Researchers have indicated the correlation between NYHA classification only in patients with non-ischemic cardiomyopathy; this correlation was independent of other risk factors (gender, smoking, alcohol consumption, hypertension, diabetes mellitus, AST, uric acid, CKMB, CRP and LVEF)." (PMID 34576235, 2021). "Univariate LR analysis of RA patients developing stroke indicated that the stratification of sex, age, SBP, CRP, ESR, TC, LDL and the history of hypertension, diabetes, AF, CVD, and CHD, were significantly different between RA with stroke and RA groups (P < 0.05) in the primary cohort." (PMID 34081620, 2021). "Furthermore, the Mann–Whitney U test showed that patients with MCI were older, less educated, had higher BMI, longer duration of diabetes, higher serum levels of HbA1c (%), TG, TC, LDL-C, hs-CRP, and TSH, and lower level of HDL-C, FT3, and FT4." (PMID 34007273, 2021). "The covariates included in the multivariable analysis were age, gender, duration of diabetes, hypertension, low-density lipoprotein cholesterol (LDL-C), hypersensitive C-reactive protein (hs-CRP), HCY, HOMA-IR, eGFR, smoke, DR, and carotid atherosclerotic plaque." (PMID 34961842, 2021). "We included age (as a categorical variable of under and over 65 years old), presence of chronic kidney disease, diabetes mellitus, coronary heart disease, and indicators, such as WBC count, NLR, CRP, PT, aPTT, and D-dimer for determining the predictors of mortality." (PMID 34904053, 2021). "Our data show a significant association between plaque accumulation and prevalent AF that is independent of age, sex, hs-CRP, BMI, smoking, diabetes, and educational status." (PMID 34807935, 2021). "We considered, separately for men and women, potential mediating effects of the following variables: CRP, creatinine, vitamin D, calcium, ALP, IGF1, SHBG, testosterone, testosterone/SHBG, estradiol, phosphate, cystatin C, hypertension, diabetes, and hypercholesterolemia." (PMID 32964541, 2021).
diabetes (continued). "Inflammatory biomarkers such as IL-6, C-reactive protein, serum ferritin, coagulation index, and D-dimer are increased in patients with diabetes compared with those without diabetes." (PMID 33585030, 2021). "In multivariate analysis, OPG was a marker of general and cardiovascular mortality independent of sex, age, CVD, diabetes, and CRP levels." (PMID 33510348, 2021). "People with diabetes infected with SARS-CoV-2 have been observed to have much higher levels of interleukin-6 (IL-6) and C-reactive protein (CRP) than individuals without diabetes." (PMID 34578858, 2021). "Individuals with diabetes have also been shown to elevate levels of the proinflammatory cytokine, especially IL-1, IL-6, and tumor necrosis factor-alpha (TNF-alpha), and different markerssuch as C reactive protein, D-dimer, and fibrinogen." (PMID 35540698, 2021). "A 10-year CVD follow-up study of Caucasian adults reported LAP to be an independent predictor of CVD; the association of LAP with CVD remained significant, even after adjusting for hypertension, diabetes, physical activity, HTG, and pro-inflammatory cytokines (C-reactive protein, IL-6, TNF-α)." (PMID 35010926, 2021). "This may be related to the inflammation that occurs in diabetes, because we observed positive correlations between VDBP and CRP levels in the T2DM group." (PMID 33728195, 2021). "A risk count is calculated by the following features on admission (1 point for each): radiographic severity score >3, male gender, non-white ethnicity, diabetes, hypertension, neutrophils >8.0 x109/L, age >40 years and CRP >40 mg/L." (PMID 32641154, 2020). "Indeed, C-reactive protein (CRP), a marker of inflammation, predicts future development of hypertension and diabetes mellitus better than body mass index." (PMID 32443535, 2020). "However, associated factors of relapse or severe complications were various (i.e., age, hypertension, diabetes at GCA diagnosis, ischemic heart disease, cranial signs and symptoms, CRP at baseline, and dose of PSL at baseline)." (PMID 32264967, 2020). "Mean body mass index, HbA1C, and hs-CRP values were significantly higher in the CKD group than in the control group after adjusting for age, sex, drinking, smoking, and the prevalence of hypertension and diabetes (p < 0.05)." (PMID 32708997, 2020). "The best-fit model included sex, SBP, diabetes, education, triglyceride, UACR, and CRP." (PMID 32252667, 2020). "These variables also correlated positively with the presence of diabetes, impaired fasting glucose, HbA1c, hypertension, male sex, age, BMI, cardiac troponin T (cTnT), and coronary calcium score (CACS) as well as with CRP and the cell count of several different leukocyte types." (PMID 32638456, 2020). "In general, patients with obesity, compared with patients without obesity, more often had diabetes and insulin resistance, a blood glucose level ≥100 mg/dL, and higher levels of C-reactive protein, and they were less physically active at baseline." (PMID 33357306, 2020). "After adjusting for age, gender, BMI, hypertension, diabetes, total cholesterol/HDL-C, triglyceride, eGFR, uric acid, calcium, highest quartile of CRP, smoking, alcohol consumption, and regular exercise, KSD was positively related to increased arterial stiffness (OR, 1.344; 95% CI, 1.095–1.649)." (PMID 32498283, 2020). "Patients in the highest NLR quartile (quartile 4) had significantly higher C-reactive protein (P=0.018) and CrCl levels (P=0.002), more PVD (P=0.027), more insulin-dependent diabetes mellitus (P=0.018), more likely to smoke (P<0.001), and were also significantly older (P=0.003)." (PMID 32549098, 2020). "In our study, the best nutritional predictor of mortality was forearm circumference, while other clinical, rather than nutritional parameters predicted re-hospitalization rate (CRP level, eGFR < 15 mL/min, and ONS use) and two-year mortality (cancer, diabetes, ONS use)." (PMID 33379274, 2020).
diabetes (continued). "Researchers have shown a positive relationship between CRP and UAE in either type 1 or 2 diabetes." (PMID 33447179, 2020). "Due to the fact that there are relatively few data on other inflammatory factors in the included original studies, our study only analyzed CRP, TNF-α, and IL-6; other inflammatory factors that affect and participate in the course of diabetes should be explored in future research." (PMID 33456672, 2020). "After adjusting for BMI and other confounding factors, multivariate Cox proportional hazards regression analysis showed that TyG index, age, previous MI, LVEF, hs-CRP and statin use independently predicted the occurrence of MACE in patients with diabetes and ACS." (PMID 32534586, 2020). "In addition, age, BMI, diabetes mellitus, previous CVD events, acute treatment, CRP, copeptin, BNP and the NIHSS score were significant MACCE predictors, unlike others factors." (PMID 32771014, 2020). "The conventional cardiometabolic risk factors did not explain the associations between CRP and PAD and/or nephropathy in diabetes and non-diabetes." (PMID 32665312, 2020). "After adjusting for onset age of diabetes, SBP, DBP, TC and CRP, the results illustrated that age and HSP27 were still independently associated with carotid IMT in type 2 diabetes, with adjusted odds ratios of 1.061 (P = 0.028) and 1.085 (P = 0.022), respectively." (PMID 32334520, 2020). "Fluoroquinolone-containing regimens were generally selected for patients with cavitary lesions, diabetes mellitus, negative culture, low daily physical activity levels, lower lymphocyte counts, and higher C-reactive protein level." (PMID 32645105, 2020). "Clinical factors did not predict FFR value; however, gender, diabetes mellitus, aortic stenosis, anemia, high-sensitivity CRP value, and renal function predicted iFR value." (PMID 32760123, 2020). "Inflammation is one of the contributing factors in developing diabetes as demonstrated by higher levels of SAA and several other inflammatory markers such as TNF, C-reactive protein (CRP), and MCP-1 that parallel increased urinary albumin secretion in such subjects." (PMID 32075280, 2020). "Separate investigations have further noted a lower age-adjusted prevalence of diabetes and lower serum C-reactive protein and reduced prevalence of non-alcoholic fatty liver disease among cannabis users compared to non-users." (PMID 33526125, 2020). "Shortness of breath at admission, past histories of diabetes and heart disease, and abnormalities in the 28 indicators, such as CD4 percentage and CRP, indicate that the patient is already severely ill or has a significant risk of progressing to severe conditions." (PMID 32766268, 2020). "It turned out that measuring IL-8 in urine along with serum CRP and neutrophil-lymphocyte ratio (NLR) could indicate the pathogen among adults with type 2 diabetes mellitus." (PMID 33299741, 2020). "In the unadjusted logistic regression analysis, older age was a significant risk factor for OSA in patients with ILD, along with male sex, higher body weight, larger neck circumference, low level of C-reactive protein, diagnosis of IPF, and history of diabetes mellitus." (PMID 33017401, 2020). "According to the number of studies (n≥10), the risk of publication bias was analyzed in the following variables: gender, age, fever, cough, diabetes, hypertension, COPD, malignancies, cardiovascular disease, cerebrovascular disease, chronic renal disease, D-dimer, and CRP." (PMID 33234724, 2020). "The median CRP concentration and proportion of participants with CRP >3 mg/L were higher in participants with diabetes than those without diabetes." (PMID 32665312, 2020). "Although there are some differences in values, but that study, like the present study, showed that serum inflammatory markers including CRP, ESR and WBC could be used for the diagnosis of foot infections in patients with diabetes." (PMID 33134967, 2020).
diabetes (continued). "The impact of DPP-4i on CRP had not been modulated by potential variables of regions, dose, age, baseline CRP and HbA1c, except for diabetes duration." (PMID 31208420, 2019). "Individuals with VEF were more likely to have lower percentages or levels of current smoking, BMI, systolic blood pressure, heart rates, serum CRP, serum total cholesterol, serum triglyceride, serum LDL cholesterol, and diabetes but a higher level of serum HDL cholesterol." (PMID 35530249, 2019). "The development of an infection was independent of the CRP-value (p = 0.66) as well as the presence of diabetes mellitus (p = 0.64) or immunosuppression (p = 0.71)." (PMID 31151433, 2019). "Moreover, when models were concurrently adjusted for gender, age, apoB concentration, diabetes, past CVD history, CRP concentration, and eGFR; again significant interaction with UAE was demonstrated only for apoA-I/HDL-C." (PMID 30813431, 2019). "Studies using the inflammatory cytokines interleukin-6 (IL-6) C-reactive protein, and tumor-necrosing-factor alfa (TNF-α) have shown that regardless of the presence of diabetes these markers are associated with the occurrence of microalbuminuria and mortality." (PMID 30997790, 2019). "Adjusting for age, gender, smoking, body mass index, hypertension, diabetes mellitus, Lp-PLA2 activity (HR 1.33; 95% CI 1.17–1.52), Lp-PLA2 mass (HR 1.20; 95% CI 1.05–1.37) and CRP (HR 1.55; 95% CI 1.36–1.76) remained independently associated with incident PAD." (PMID 30948779, 2019). "In the present study, serum CRP levels were significantly higher in patients with diabetes than in the non-diabetic patients." (PMID 31372137, 2019). "In fact, elevated levels of inflammatory markers [interleukin-1β (IL-1β), tumour necrosis factor-α (TNF-α), interleukin-6 (IL-6), interleukin-8 (IL-8), and C-reactive protein (CRP)] were shown to increase neutrophil apoptosis and impair neutrophil clearance in patients with diabetes." (PMID 31827375, 2019). "After multivariate adjustment, older age, longer duration of PD, presence of diabetes, comorbid CVD, use of 2.5% glucose dialysate, higher CRP, lower BMI, and lower albumin and phosphate levels continued to be independently associated with increased HR for all-cause mortality." (PMID 30850727, 2019). "Assessed baseline characteristics of enrolled patients included Gender, Age, Smoker or not, Hypertension, Diabetes, BMI, Thrombocytes, Leukocytes, Haemoglobin, Creatininekinase, Troponin T, CRP and number of coronary Vessels involved." (PMID 31644579, 2019). "Moreover, the long-term use of dietary supplements, including multivitamin or mineral complexes showed benefits in C-reactive protein, HDL cholesterol, triacylglycerides, serum homocysteine, blood pressure and incidence of diabetes." (PMID 29568330, 2018). "Furthermore, a stepwise multiple regression analysis was performed between PTX3 and each parameter which was correlated with serum PTX3 level in univariate model, such as existence of diabetes, HbA1c, UAE, PAC, high-sensitivity CRP." (PMID 29715313, 2018). "In this study variables such as delivery type; maternal and fetal WBC and CRP; maternal age; AFI; pregnancy hypertension disease; gestational glucose intolerance; or diabetes were not significant risk factors for RDS (p = ns) in preterm neonates." (PMID 30402491, 2018). "CRP, insulin and HOMAIR were all significantly elevated in patients with diabetes." (PMID 29975702, 2018). "In the multivariate Cox regression analysis, the significance of serum Angpt-2 associated with all-cause mortality in model was lost when adjusting for age, male gender, diabetes and components of MIAC syndrome (hs-CRP, serum albumin, background VC and background AVD) (p = 0.3)." (PMID 30445969, 2018). "Moreover, C-reactive protein (CRP), an index of systemic inflammation, is overexpressed in the serum of OSCC and type 2 diabetes mellitus (T2DM) patients." (PMID 30241505, 2018).
diabetes (continued). "Current smoking, obesity, diabetes mellitus, elevated hs-CRP, and the non-use of dental devices were significantly associated with an increased risk of poor oral health after adjusting for age and sex." (PMID 29503388, 2018). "Multiple variables were different between the WL and WOL groups, including age, systolic blood pressure (SBP), postprandial blood glucose (PBG), total cholesterol (TC), apolipoprotein A-I (ApoA I), creatinine (Cr), C-reactive protein (CRP), diabetes mellitus and hypertension." (PMID 29896432, 2018). "As expected, 24 h urinary microalbumin was negatively correlated with bilirubin concentrations (r = -0.13, P < 0.05), HDL-C (r = -0.16, P = 0.01), and total GFR (r = -0.20, P < 0.001) and positively correlated with duration of diabetes, BMI, SBP, WHR, CRP, uric acid, Cr, TG levels (all P < 0.001)." (PMID 28363276, 2017). "Several potential confounders, such as age, gender, comorbidities (Diabetes Mellitus, CVD etc.), serum albumin, residual glomerular filtration rate (rGFR), and even high sensitive C-reaction protein (hs-CRP) and urea clearance (Kt) normalized to total body water (Kt/ Vurea) were taken into account." (PMID 28207885, 2017). "The general inflammation and infection parameter hs-CRP was a significant predictor for total mortality in individuals with and without diabetes." (PMID 28713837, 2017). "Adding age, eGFR, serum levels of calcium, phosphate, CRP, the presence of diabetes and the presence of VC did not improve this model." (PMID 28320782, 2017). "The impact of elevated serum hs-CRP level on the prevalence of type 2 diabetes was prominent in subjects without a family history of diabetes." (PMID 28361994, 2017). "In the SHS main cohort, baseline CRP was associated with incident CVD events, although the association was limited to participants without diabetes." (PMID 28771557, 2017). "Nevertheless, when we observe the relation between HbA1c and hs-CRP in the well-controlled and non-controlled diabetes groups separately, the correlations are not significant in the two groups." (PMID 28886725, 2017). "Our study revealed that multiple risk factors, including traditional risk factors and non-traditional risk factors such as epicardial fat accumulation as well as high CRP and low adiponectin levels, are determinants for CABG in men, but diabetes mellitus was the sole determinant in women." (PMID 28594865, 2017). "Cogent to earlier reports, our data suggest that reduced protein O-GlcNAcylation by CrP may block TSP-1 upregulation in the large vessel impeding enhanced VSMC proliferation and atherosclerotic lesion formation in diabetes." (PMID 28345659, 2017). "Bivariate correlations showed negative associations of both LPA and MVPA with age, diabetes duration, HbA1c, FPG, HOMA-IR, BMI, fat mass, waist circumference, hs-CRP, UKPDS risk scores, VO2max, strength, and SED-time." (PMID 28291838, 2017). "Data from the Italian Diabetes and Exercise Study (IDES) showed that aerobic or combined (aerobic and resistance) exercise was effective in reducing CRP plasma levels after 12 months of training in T2DM patients receiving standard medical care (nutritional guidance and pharmacological treatment)." (PMID 28400914, 2017). "Upon additional adjustment of these gene associations for smoking, LDL levels, BMI levels, the presence of diabetes mellitus, arterial hypertension, symptom-to-reperfusion time and C-reactive protein, the effect did not change significantly (p – value > 0.2)." (PMID 28155873, 2017). "The predictive role of high-sensitivity C-reactive protein (hs-CRP), number of tooth extractions, and oral infections for mortality in people with and without diabetes is unclear." (PMID 28713837, 2017).